ATL3 (atlastin GTPase 3)
Description:
Atlastin-3 (ATL3) is a membrane-anchored GTPase that mediates the GTP-dependent fusion of endoplasmic reticulum (ER) membranes, maintaining the continuous ER network. It facilitates the formation of three-way junctions where ER tubules intersect. Two atlastin-3 on neighboring ER tubules bind GTP and form loose homodimers through the GB1/RHD3-type G domains and 3HB regions. Upon GTP hydrolysis, the 3HB regions tighten, pulling the membranes together to drive their fusion. After fusion, the homodimer disassembles upon release of inorganic phosphate (Pi). Subsequently, GDP dissociates, resetting the monomers to a conformation ready for a new fusion cycle (By similarity).
Synonyms: AT3; ATL-3; DKFZP564J0863; HSN1F
Tractability: Small molecule: a structure with a bound ligand is known. Antibody: UniProt predicts a signal peptide or a membrane-spanning region. PROTAC: ubiquitination databases record sites on it; its protein half-life has been measured.
Target class: Enzyme; Hydrolase
Gene: Protein-coding gene on chromosome 11 (63,624,087 to 63,671,921, reverse strand). Ensembl gene ENSG00000184743.
Subcellular location: Endoplasmic reticulum membrane
Subcellular location (Human Protein Atlas): Endoplasmic reticulum
Gene Ontology:
Molecular function: GTPase activity; GTPase-dependent fusogenic activity; identical protein binding; protein binding; GTP binding
Biological process: endoplasmic reticulum membrane fusion; endoplasmic reticulum to Golgi vesicle-mediated transport; endoplasmic reticulum tubular network membrane organization; endoplasmic reticulum organization; protein homooligomerization
Cellular component: endoplasmic reticulum; endoplasmic reticulum membrane; endoplasmic reticulum tubular network; endoplasmic reticulum tubular network membrane; membrane
Genetic constraint (gnomAD): Loss-of-function variants: 39 observed, 57.14 expected, observed/expected ratio (o/e) 0.68, 90% interval 0.53 to 0.89. The upper end of that interval is the gene's LOEUF score, 0.89, which puts it in group 3 of 6, group 1 being the genes least tolerant of losing a copy. Missense variants: 540 observed, 586.02 expected, observed/expected ratio (o/e) 0.92, 90% interval 0.86 to 0.99. Synonymous variants: 194 observed, 210.59 expected, observed/expected ratio (o/e) 0.92, 90% interval 0.82 to 1.04.
Gene-disease validity (ClinGen):
ClinGen rates the evidence that ATL3 causes each of these diseases.
neuropathy, hereditary sensory, type 1F (autosomal dominant): Moderate. Any hereditary sensory and autonomic neuropathy type 1 in which the cause of the disease is a mutation in the ATL3 gene.
Homologues: Orthologues: macaque ATL3 (99% identical), chimpanzee ATL3 (97% identical), guinea pig ATL3 (96% identical), mouse Atl3 (95% identical), rat Atl3 (94% identical), dog ATL3 (92% identical), rabbit ATL3 (92% identical), pig ATL3 (89% identical), tropical clawed frog atl3 (76% identical), zebrafish atl3 (65% identical), Caenorhabditis elegans atln-1 (54% identical). Paralogues in human: ATL2 (62% identical), ATL1 (61% identical), GBP4 (23% identical), GBP1 (22% identical), GBP2 (22% identical), GBP3 (22% identical), RNF112 (21% identical), GBP5 (21% identical), GBP6 (21% identical), GBP7 (21% identical).
Diseases named in the same sentence as ATL3 in open-access papers:
ATL3 is named in the same sentence as 25 diseases in open-access papers, as found by Europe PMC text mining. Sharing a sentence is not in itself a finding about the gene and the disease. The quoted sentences say what the papers report.
hereditary sensory and autonomic neuropathy (7 papers, 2015 to 2024). An instance of sensory peripheral neuropathy that is caused by an inherited modification of the individual's genome. "Loss-of-function mutations in two RHD-containing ER-phagy receptors, FAM134B and ATL3, lead to hereditary sensory neuropathies (HSAN) caused by the decreased survival of sensory and autonomic neurons." (PMID 35452617, 2022). "ATL3 has also been implicated in human disease as its mutation is responsible for hereditary sensory and autonomic neuropathy (HSAN)." (PMID 34831093, 2021). "In addition to their role in HSP, familial mutations in ATL1 and ATL3 have been found to cause hereditary sensory neuropathy (HSN), another neurodegenerative disorder affecting sensory neurons." (PMID 34808209, 2022). "While the HSP-associated mutation presented here demonstrates a novel gain-of-function disease mechanism in ATL1, a recent study characterized two gain-of-function mutations in ATL3 (Y192C and P338R) that had been identified in hereditary sensory neuropathy patients." (PMID 34808209, 2022). "ATL1 and ATL3 are also found mutated in hereditary sensory and autonomous neuropathy (HSAN)." (PMID 26744348, 2016). "Notably, low levels of ATL3 are also found in brain tissue, which is consistent with a recent description of a rare case in which ATL3 mutation caused hereditary sensory neuropathy." (PMID 25773277, 2015). "This notion is strengthened by the fact that mutation in ER morphology and degradation-regulating proteins, including ATL1, ATL3, REEP, and FAM134, are common causes of the motor neuron diseases hereditary spastic paraplegia (HSP) and hereditary sensory and autonomic neuropathy (HSAN)." (PMID 36960757, 2024).
Sensory neuropathy (3 papers, 2019 to 2023). Peripheral neuropathy affecting the sensory nerves. "Patients presenting with mutations in ATL3 developed signs of sensory neuropathy affecting lower limbs, bone destruction of toes, recurrent foot ulcerations, osteomyelitis, decrease in superficial sensation, and in some cases, absence of tendon reflexes." (PMID 37371660, 2023). "Meanwhile, pathogenic variants in ATL3, which belongs to the Atlastin family of proteins mediating ER morphology, also cause sensory neuropathy and increase mt-ER contacts leading to impaired axonal mitochondrial distribution." (PMID 33810506, 2021). "We here show that the sensory neuropathy causing ATL3 Y192C mutation reduces the complexity of the tubular ER-network." (PMID 30666337, 2019). "Herein, by analyzing targeted-NGS data of a patient presenting with sensory neuropathy symptoms using the CovCopCan bioinformatic tool, we discovered the presence of a deletion of around 3kb in ATL3 from Chr11:63,401,422 to Chr11:63,398,182." (PMID 37371660, 2023). "To conclude, our approach of analyzing NGS data, not only looking for SNVs but also SVs, allowed us to detect a 3kb deletion in ATL3 in a patient presenting with sensory neuropathy symptoms." (PMID 37371660, 2023).
and autonomic neuropathy (2 papers, 2020 to 2021). "Some of these adaptors such as FAM134B, ATL3 or RTN3L are highly expressed in the brain, and point mutations in FAM134B or ATL3 are associated to hereditary sensory and autonomic neuropathies though mechanisms are still poorly understood." (PMID 33340068, 2021). "Interestingly, the ER fusion protein atlastin 3 (ATL3) has been identified in patients with hereditary sensory and autonomic neuropathy." (PMID 33071754, 2020).
COVID-19 (1 paper, 2021). A disease caused by infection with severe acute respiratory syndrome coronavirus 2. "ATL3 as mentioned is also included in the “COVID-19-specific gene signature” and is under-expressed in COVID-19." (PMID 33437935, 2021). "ACO1 was over-expressed in COVID-19 versus HC and under-expressed in non-COVID-19 viral infections versus HC, whereas ATL3 entirely oppositely regulated." (PMID 33437935, 2021). "Since the “COVID-19-specific gene signature” is derived from direct comparison of COVID-19 versus non-COVID-19 infections, ZC3H13, AMIGO1, and ATL3 under-expressed in COVID-19 equates to higher expression in non-COVID-19 infections." (PMID 33437935, 2021).
hereditary sensory neuropathy type 1F (1 paper, 2023). "Heterozygous mutations in ATL3 have been reported to result in hereditary sensory neuropathy type 1F (HSN1F; OMIM #615632)." (PMID 37371660, 2023).
melanoma (1 paper, 2021). A malignant, usually aggressive tumor composed of atypical, neoplastic melanocytes. "Investigating negative-regulated target genes, we found eight genes (ANKRD13C, ARL5A, ATL3, PAWR, PDCD6IP, SLC16A7, TFAM, UBP1) presenting a significant inverse correlation with miR-181a/b expression also in melanoma A375 sensitive cells." (PMID 33670365, 2021).
neuropathies (1 paper, 2023). "The data expand the spectrum of disease-relevant alterations in CIP/HSAN, including novel variants in previously rarely recognized entities such as ATL3-, FLVCR1- and NGF-associated neuropathies and previously under-recognized mutation types such as larger deletions." (PMID 37769650, 2023).
progeria (1 paper, 2023). "Consistent with previous results, Btg2, p21, IL6, Mmp12, and Atl3 were significantly downregulated by the dCas9‐Oct4 activator in these tissues of progeria mice." (PMID 36964992, 2023).
prostate carcinoma (1 paper, 2025). A carcinoma that arises from epithelial cells of the prostate gland. "Several additional tumor suppressors were similarly affected by promoter-closing variants, including BBC3 (PUMA), a pro-apoptotic gene that suppresses prostate cancer cell growth, and known tumor suppressors, ATL3 and ING5." (PMID 41468516, 2025).
Spastic paraplegia (1 paper, 2019). Complete loss of the ability to move the lower limbs accompanied by spasticity of the lower limbs. "Mutations in ATL1 and ATL3 cause spastic paraplegia and hereditary sensory neuropathy." (PMID 30666337, 2019).
tumor (3 papers, 2025). "Specifically, ATL3 expression has been associated with the inhibition of metastatic potential and impaired tumor cell survival." (PMID 39858632, 2025). "Extensive studies using GI cancer models have revealed that AMK compounds, especially ATL-1 and ATL-3, inhibit tumor growth through the TLR4/MyD88 pathways and mitochondrial signaling." (PMID 40144663, 2025). "Moreover, findings suggesting the tumor-suppressive properties of IR-induced SASP including ATL3 and ERGIC1 also align well with earlier studies." (PMID 39858632, 2025). "In contrast, factors like ATL3 (Log2 ratio 1.40), ERGIC1 (Log2 ratio 1.64), SPON1 (Log2 ratio 1.25), TNFAIP8 (Log2 ratio 1.99), and VDAC1 (Log2 ratio 1.20), associated with a “highly favorable” prognosis, suggest roles in tumor suppression." (PMID 39858632, 2025). "Conversely, SASP factors such as ATL3 and ERGIC1 demonstrated favorable prognostic outcomes, indicating potential tumor-suppressive roles." (PMID 39858632, 2025).
neurological diseases (2 papers, 2017 to 2022). "Moreover, we identified 3 upregulated [ENO3, LPIN1 and SCN9A] and 3 downregulated [ATL3, CPT1C, and SGCB] RNAs whose genes have been implicated in neurological disorders." (PMID 34907471, 2022).
bacterial infection (1 paper, 2018). "The ectopic production of dominant-negative GFP-Sey1_K154A (or depletion of Atl3 by RNAi) allowed us to study the involvement of a major cellular regulator of ER homeostasis during the bacterial infection cycle." (PMID 30083282, 2018).
infection (1 paper, 2021). The state of being infected such as from the introduction of a foreign agent such as serum, vaccine, antigenic substance or organism. "Lack of ATL3 results in delayed cargo exit and coat assembly for budding from the ER which is necessary for export of cytokines and chemokines in response to infection; ATL3 has been linked directly to viral replication in Zika, although Zika was not studied here." (PMID 33437935, 2021).
neurodegenerative disease (1 paper, 2021). A disorder of the central nervous system characterized by gradual and progressive loss of neural tissue and neurologic function. "Mutations in ATL3 and ATL1 have been linked to neurodegenerative diseases, which may be caused by impaired ER-phagy." (PMID 34571977, 2021).
peripheral neuropathy (1 paper, 2021). A disorder affecting the peripheral nervous system. "Mt-ER contacts, which are impacted by variants in several peripheral neuropathy proteins (e.g., MFN2, GDAP1, ATL3), are important for mediating mitochondrial function, but are also important for mitochondria fission, motility, and likely by extension quality control." (PMID 33810506, 2021).
ATL3 also shares sentences with these, for which no sentence is quoted: asthma (1 paper); breast carcinoma (1); cancer (1); dengue (1); heart failure (1); hereditary spastic paraplegia (1); lung carcinoma (1); renal carcinoma (1); viral infections (1).